TGFBR1 (transforming growth factor beta receptor 1)
Diseases named in the same sentence as TGFBR1 in open-access papers (continued):
Sharing a sentence is not in itself a finding about the gene and the disease.
lung carcinoma (32 papers, 2007 to 2025). "TGFBR1 inhibitors show synergy with existing therapeutics in treating GATA4-deficient lung cancers in genetically engineered mouse model as well as patient-derived xenograft (PDX) mouse models." (PMID 30971692, 2019). "We went on to treat GATA4-deficient lung cancer through targeting TGFBR1 using transgenic mouse models." (PMID 30971692, 2019). "Hence, for association of Tgfbr1 mutations with lung cancer, a large-scale case-control study on mutations of its transcript is required to test any correlation between the frequency of mutated transcripts and their potential to cause malignancy." (PMID 17705854, 2007). "Moreover, we showed that TGFBR1 inhibition could suppress the malignant progression of GATA4-deficient lung cancer." (PMID 30971692, 2019). "In lung cancer studies, miR-34b-3p upregulation targets TGFBR1 (transforming growth factor beta type I receptor) in A549 and H1299 cell lines." (PMID 40808836, 2025). "SMASR interacted directly with SMAD3, and their complex associated with the chromatin of the TGFBR1 gene causing its repression, thus limiting TGF-β signaling and lung cancer EMT." (PMID 38571882, 2024). "TGFBR1 is a crucial inducer of lung cancer progression, and inhibition of TGFBR1 effectively reduces bone metastasis in prostate cancer." (PMID 38287071, 2024). "It has been further reported that CLU inhibits lung cancer progression by inhibiting TGFBR1-induced TRAF6/TAB2/TAK1 complex recruitment and thus blocking the TAK1-NF-κB axis, indicating its tumor-suppressive function, which is consistent with our in vivo data." (PMID 35626071, 2022). "First, to our best knowledge, this is the first report showing that miR-769-5p is down-regulated in NSCLC, which is negatively correlated with the expression of TGFBR1, a newly discovered target in lung cancer." (PMID 29371929, 2017). "Reduced expression of TGFBR1 by siRNA suppressed the invasive ability of a human lung carcinoma cell line, A549 cells." (PMID 25938468, 2015). "recently reported that the interaction between YBX1 and lncRNA RMRP could subsequently activate TGFBR1 expression in nonsmall cell lung cancer." (PMID 37867401, 2023). "Importantly, IGF2BP2 could stabilize TGFBR1 expression, thus mediating the promotion of M2 macrophage polarization and lung cancer malignant process." (PMID 39014364, 2024). "It is also reported that in lung cancer TGFBR1 may be a target of tumor suppressor genes." (PMID 32582282, 2020). "Finally, we showed that TGFBR1 had opposite effects to those of miR-769-5p on lung cancer cells, suggesting that miR-769-5p might inhibit lung tumorigenesis by silencing TGFBR1." (PMID 29371929, 2017). "TGF-β2 signals through TGFBR1, TGFBR2, SMAD2, and SMAD4 to upregulate WNT7B mRNA expression in lung cancer cells." (PMID 30971692, 2019). "In the top 50 potential lung cancer-related miRNAs, miR-133a plays a tumor suppressor role in non-small cell lung cancer (NSCLC) by targeting IGF-1R, TGFBR1 and EGFR." (PMID 29498680, 2018). "The oncogenic receptors in lung cancer cells, including insulin-like growth factor 1 receptor (IGF-1R), TGF-beta receptor type-1 (TGFBR1), and epidermal growth factor receptor (EGFR), are direct targets of miR-133a." (PMID 24816813, 2014). "MiR-133a can inhibit cell invasiveness and cell growth through suppressing the expressions of IGF-1R, TGFBR1 and EGFR, which then influences the downstream signaling in lung cancer cell lines." (PMID 24816813, 2014). "TGFBR1 inhibitors can significantly inhibit the growth of tumor cells in lung cancer lacking the tumor suppressor GARA4 and can be used as a potential therapeutic target." (PMID 36308553, 2023). "In previous studies, Y-box sequence, as a cis-acting element, up-regulated ceramide synthase 6 through the transcriptional regulation of YBX1 to promote lamellipodia formation as well as migration activity, and up-regulated TGFBR1 to promote the stemness and EMT of lung cancer cells." (PMID 34976785, 2021).
lung carcinoma (continued). "To test whether this was also true in lung cancer cells, we generated H460 for Dox inducible expression of Clusterin (designated H460-tet-CLU) and found that CLU expression effectively inhibited recruitment of TRAF6 by TGFBR1." (PMID 33052230, 2020). "In addition, knockdown of FLJ20420 expression also significantly increased the expression of PRKCBP2, TGFBR1, TGFB2, CLCN4, TRAF3, MYLK and ACTA2, while decreasing the expression of SMAD5 and prot-LBC, resulting in an increased apoptotic potential in FLJ20420-silenced lung cancer cells." (PMID 22567091, 2012).
pulmonary fibrosis (32 papers, 2013 to 2026). Chronic progressive interstitial lung disorder characterized by the replacement of the lung tissue by connective tissue, leading to progressive dyspnea, respiratory failure, or right heart failure. "TGFBR1 gene mutation mediates the development of cancers, myocardial fibrosis, and pulmonary fibrosis." (PMID 40166052, 2025). "SNHG20, a newly identified lncRNA, has been found to participate in the process of vasculogenic mimicry and was associated with pulmonary fibrosis through the microRNA 490-3p (miR-490-3p)/TGFBR1 axis." (PMID 40443971, 2025). "Decreased TGFBR1 exerted an antifibrotic effect in silica-induced pulmonary fibrosis by suppressing TGF-β1 signaling pathway." (PMID 40166052, 2025). "A recent study proved that miR-770-5p suppressed the activation of pulmonary fibroblasts and further inhibited silica-induced pulmonary fibrosis by targeting transforming growth factor beta receptors (TGFBR1)." (PMID 39866352, 2024). "It is also noteworthy that a combination treatment of PDGFR (imatinib) and TGFBR1 (galunisertib) inhibitors was more effective than blockade of either pathway alone in a murine radiation-induced lung fibrosis model." (PMID 39656528, 2024). "Upregulated TXNDC5 can enhance TGFβ1 signaling by promoting the folding and stabilization of TGFBR1 in lung, leads to pulmonary fibrosis (PF)." (PMID 38629066, 2024). "In vascular and pulmonary fibrosis, let-7i-5p inhibits endothelial to mesenchymal transition (EndoMT) or fibroblast activation by targeting Tgfbr1." (PMID 36091385, 2022). "In the present study, MHP1-AcN decreased TβRI and TβRII expression in fibroblasts, but in bleomycin-induced lung fibrosis model, MHP1-AcN treatment inhibited the increase in Tgfbr2 without significant change in Tgfbr1 on day 14 after bleomycin exposure." (PMID 35864207, 2022). "Here the authors show that a fibroblast-enriched endoplasmic reticulum protein, TXNDC5, promotes pulmonary fibrosis by stabilizing TGFBR1 and show the potential of TXNDC5 as a therapeutic target against pulmonary fibrosis." (PMID 32848143, 2020). "Moreover, TGFBR1 also contributed to pulmonary fibrosis and non-small cell lung cancer (NSLC) by interacting with let-7i-5p and miR-98-5p, respectively." (PMID 37187956, 2023). "MiR-490-3p is also involved in silicon-induced pulmonary fibrosis by targeting TGFBR1 modulators." (PMID 36937888, 2023). "TXNDC5 promotes pulmonary fibrosis by augmenting TGFβ signalling through TGFBR1 stabilization." (PMID 36160018, 2022). "The results presented here showed that TXNDC5 promotes lung fibrosis by enhancing TGFβ signaling activity via post-translational stabilization of TGFBR1 in lung fibroblasts, thereby leading to excessive lung fibroblast activation, proliferation, and ECM production." (PMID 32848143, 2020). "Viral induction of TGFB1 predicts profibrotic signaling to most epithelial cells and fibroblasts expressing both TGFBR1 and TGFBR2, including myofibroblasts, which constitute the fibroblast foci in lung fibrosis." (PMID 38597954, 2024). "TargetScan predicted that miR-125b-5p and miR-615-3p target TGFBR1 (TGF-β receptor 1), suggesting that they may regulate lung fibrosis through TGF-β." (PMID 41463319, 2025). "Collectively, these results suggest that ANRIL promotes fibroblast activation and fibrosis development, possibly through the let-7d-5p/TGFBR1 axis, indicating that ANRIL could be a potential therapeutic target for pulmonary fibrosis." (PMID 39612365, 2024). "Moreover, miR-3934-3p have been found to down-regulate TGFBR1 and SMAD3 which are critical players for lung fibrosis and have been previously reported in SARS-CoV-related cases." (PMID 37053191, 2023). "Since IR slightly induced mRNA of TGFβ, TGFBR1, and Smad 6 especially in 90Gy irradiated lungs, TGFβ-mediated direct or indirect EMT mechanisms by IR may involve in expression of these two gene expressions during lung fibrosis." (PMID 30406363, 2019).
colorectal cancer (31 papers, 2009 to 2024). A primary or metastatic malignant neoplasm that affects the colon or rectum. "miRs in hsa‐let‐7 family have been suggested to increase colorectal cancer risk in path_MMR carriers with proficient MMR by lowering the expression of TGFBR1 haplotype." (PMID 36282188, 2023). "Mutations in the TGFBR1 gene induce tumorigenesis and promote tumor metastasis, which are associated with increased risk of breast, ovarian, and colorectal cancers." (PMID 36712672, 2022). "ASE of APC and TGFBR1, for example, is known to be associated with colorectal cancer (CRC), with the frequency of ASE in both APC and TGFBR1 reportedly increased up to 10-fold in CRC compared to controls." (PMID 31093489, 2019). "Several studies support this notion: TGFBR1 mutations increase the overall risk of colorectal cancer and loss of SMAD4 in colon cancer results in worse survival and earlier recurrence." (PMID 27270652, 2017). "Examples include ASE of the APC and TGFBR1 gene which has been associated with colorectal cancer or ASE of BRCA1 and BRCA2 in breast cancer." (PMID 23383130, 2013). "TGFBR1*6A is emerging as a high frequency, low-penetrance tumor susceptibility allele that confers susceptibility to breast, ovarian, and colorectal cancer." (PMID 21071884, 2011). "Studies are currently in progress to validate the association of TGFBR1 SNPs with colorectal cancer risk." (PMID 20500843, 2010). "Constitutively decreased TGFBR1 allelic expression is emerging as a potent modifier of colorectal cancer risk in mice and humans." (PMID 20500843, 2010). "The association of this phenotype with TGFBR1*6A, rs7034462 and rs1156875 suggests an association between TGFBR1 SNPs and colorectal cancer, which warrants additional studies." (PMID 20500843, 2010). "The authors assumed that if TGFBR1 ASE were a driver of colorectal cancer, the lower expression of one TGFBR1 allele should likely also be evidenced in colon epithelial cells from affected individuals." (PMID 20500843, 2010). "This led to the identification of two novel haplotypes associated with decreased TGFBR1 allelic expression and markedly increased risk of colorectal cancer." (PMID 20500843, 2010). "Because of this controversy, we conducted a case-control study of the TGFBR1*9A/6A polymorphism, including mutational and ASE analyses, to clarify the effect of the TGFBR1*6A polymorphism on the risk of colorectal cancer in our population." (PMID 19538729, 2009). "It has been suggested that the TGFBR1*6A allele is a low-penetrance susceptibility factor for colorectal cancer." (PMID 19538729, 2009). "The aim of this study was to assess the association between TGFBR1*6A and colorectal cancer, age, sex, tumour location and tumour stage in a Spanish population." (PMID 19538729, 2009). "We crossed Tgfbr1 haploinsufficient mice with ApcMin/+ mice, one of the most commonly used models of colorectal cancer, and found that constitutively decreased Tgfbr1 signaling is a potent modifier of colorectal cancer risk." (PMID 20500843, 2010). "To test the hypothesis that constitutively decreased TGFBR1 signaling modifies colorectal cancer risk, we developed a novel mouse model of Tgfbr1 haploinsufficiency." (PMID 20500843, 2010). "Variants of the transforming growth factor-beta receptor type 1 (TGFBR1) gene, TGFBR1*6A and Int7G24A, have been suggested to act as low-penetrance tumour susceptibility alleles with TGFBR1*6A being causally responsible for some cases of familial colorectal cancer (CRC)." (PMID 19401691, 2009). "Thus, the TGFBR1*6A allele, located at exon 1 (rs11466445) has been shown to be a susceptibility allele for colorectal cancer (CRC), breast and ovarian cancers, based on a meta-analysis of many case-control studies." (PMID 19930569, 2009). "In addition, previous study has also reported that it could confer an increased risk of colorectal cancer by affecting TGFBR1 expression." (PMID 30479570, 2018).
colorectal cancer (continued). "Similar observations of increased growth and invasion were reported in colorectal cancer cells that endogenously harbor TGFBR1*6A." (PMID 35853889, 2022). "Gu and colleagues have found a correlation between colorectal cancer and the SNP rs1590 of transforming growth factor-b (TGFBR1), which acted as a promoter or tumor suppressor depending on the cellular context." (PMID 35330456, 2022). "A similar increase in MAP-kinase activation has also been correlated with increased invasion of TGFBR1*6A-transfected colorectal cancer cells." (PMID 35853889, 2022). "Among these miRNAs, the expression of miR-2117 was observed in colorectal cancer inversely correlated with the expression levels of the target gene TGFBR1." (PMID 34315420, 2021). "This provides additional evidence of a central role for TGFBR1*6A in colorectal cancer, especially as it relates to the TGFBR1 ASE phenotype." (PMID 20500843, 2010). "Our findings confirm our original discovery of a high frequency of constitutively decreased TGFBR1 allelic expression in patients with colorectal cancer." (PMID 20500843, 2010). "In this cross sectional study of 118 consecutively-recruited patients with colorectal cancer 74 (62.7%) individuals were heterozygous for informative TGFBR1 SNPs." (PMID 20500843, 2010). "In a mice model, constitutively reduced TGFBR1-mediated TGF-β signaling significantly enhances colorectal cancer development and more rapid tumor cell proliferation." (PMID 20429896, 2010). "In summary our results confirm the high frequency of the TGFBR1 ASE phenotype among patients with colorectal cancer and suggest a central role of the TGFBR1 locus in the etiology of this disease." (PMID 20500843, 2010). "Recently, it has been suggested that a mouse model carrying a germline Tgfbr1 haploinsufficiency has constitutively reduced TGF-beta signalling that significantly enhances the development of colorectal cancer." (PMID 19538729, 2009). "Wfdc3 encodes a member of the WAP-type four-disulfide core (WFDC) domain family, which functions as a protease inhibitor, promoting the ERβ-mediated transcriptional repression of TGFBR1 in colorectal cancer, thus showing a link between WFDC3 and oestrogen receptor." (PMID 39518930, 2024). "Although some studies have suggested that the TGFBR1*6A allele confers an elevated risk of colorectal cancer, most studies have not found such an association." (PMID 24981199, 2014). "We have previously shown that TGFBR1*6A, one of the SNPs previously associated with the TGFBR1 ASE phenotype, is somatically acquired in the normal appearing colonic epithelium of a small proportion of patients with colorectal cancer." (PMID 20500843, 2010). "Our results suggest that the TGFBR1*6A allele does not confer an increased risk of colorectal cancer in the Spanish population." (PMID 19538729, 2009). "Taken together, our results strongly suggest that the TGFBR1*6A allele does not confer an increased risk of colorectal cancer in the Spanish population." (PMID 19538729, 2009). "Since miRNA-638 has been reported to be down-regulated to promote apoptosis and autophagy by Rh2 in several cancer cell types, other miRNAs may also be involved in the development of colorectal cancers, such as TGFBR1:miR-532-5P, SMAD7:miR-375, PI3KCA:miR-520a, and CD44:miR-509-3P." (PMID 37764996, 2023). "In addition, the TGFBR1*6A variant has been proposed to be directly causally responsible for a proportion of hereditary non-polyposis colorectal cancer (HNPCC), especially those without MMR deficiency." (PMID 19401691, 2009). "Inhibition of TGFBR1 can block the activation of fibroblasts mediated via IL1B/TGFB1 and reduce the secretion of pro-inflammatory cytokines in colorectal cancer, which would make the cancer cells more sensitive to chemotherapy." (PMID 32582282, 2020).
colorectal cancer (continued). "In colorectal cancer models, TGF-β was shown to be a major driver of immune exclusion and evasion that could be reversed by the TGFBR1 inhibitor galunisertib in combination with PD-L1 blockade." (PMID 38622286, 2024). "A recent report suggests that the TGFBR1 ASE phenotype is non-existent in patients with sporadic colorectal cancer." (PMID 20500843, 2010).